CCR6 (C-C motif chemokine receptor 6)
Diseases named in the same sentence as CCR6 in open-access papers (continued):
Sharing a sentence is not in itself a finding about the gene and the disease.
chronic pancreatitis (2 papers, 2010 to 2023). A chronic inflammatory process causing damage and fibrosis of the pancreatic parenchyma. "CCR6 has also been related to chronic pancreatitis in a single-cell sequencing analysis with pancreatic immune cells." (PMID 37092451, 2023). "Here, we comparatively investigated the expression profile and clinical significance of the CCL20/CCR6 system in PCA as well as in chronic pancreatitis (CP) and pancreatic cystadenoma (PA) which represent pre-malignant conditions often preceding the development of PCA." (PMID 20459729, 2010). "Single-cell sequencing revealed that the CCR6/CCL20 axis is upregulated in hereditary chronic pancreatitis when compared with idiopathic chronic pancreatitis; therefore, this signaling pathway could be a potential target in human hereditary chronic pancreatitis." (PMID 37092451, 2023).
dengue (2 papers, 2023). "Treatment of purified naïve CD4+ T cells with EVs derived from severe dengue plasma drove CD4+ proliferation toward specific subtypes and modulated surface receptor CXCR3 and CCR6 expression." (PMID 37982662, 2023).
endothelial dysfunction (2 papers, 2020 to 2024). In vascular diseases, endothelial dysfunction is a systemic pathological state of the endothelium (the inner lining of blood vessels) and can be broadly defined as an imbalance between vasodilating and vasoconstricting substances produced by (or acting on) the endothelium. "This strong increase in systemic inflammation is associated with endothelial dysfunction as assessed by D-dimers, and hyperactive CCR6+Th17+ T cells locally in the lung." (PMID 32838341, 2020). "During atherogenesis, endothelial dysfunction elevates local CCL20 levels, directing CCR6 cells (B cells, immature dendritic cells, innate lymphoid cells (ILCs), regulatory CD4 T cells, and Th17 cells) to the subendothelial space." (PMID 39335632, 2024).
esophageal cancer (2 papers, 2017 to 2025). A primary or metastatic malignant neoplasm involving the esophagus. "The differences of the CCR6 expression and the functional experimental study between esophageal cancer cell lines ECA-109 and TE-1 may be caused by the different degrees of differentiation in the ESCC cell lines." (PMID 29383156, 2017).
gastric tumor (2 papers, 2023 to 2024). "Ccr6+ and Ccr6− gastric tumor–infiltrating CD45+ immune cells from PpardTG mice were then sorted by flow cytometry." (PMID 37572185, 2023). "PPARδ dysregulation of Ccl20/Ccr6 axis promotes GAC carcinogenesis by remodeling gastric tumor microenvironment." (PMID 37572185, 2023). "CCR6 is a non-promiscuous chemokine receptor that has only one known chemokine ligand, CCL20, and commonly exists on T cells and myeloid cells, the majority of gastric tumor–infiltrating immune cells in PpardTG mice." (PMID 37572185, 2023).
glioblastoma (2 papers, 2018 to 2022). The most malignant astrocytic tumor (WHO grade IV). "CCR6 was expressed at similar proportions between blood and glioblastoma specimens for all CD8+ T-cell subsets." (PMID 35464424, 2022). "Within glioblastoma-infiltrating T cells, a large proportion of cells were positive for CXCR4 and the proportion of cells positive for chemokine receptors CCR4, CCR5, CCR6, CCR7, CXCR3, and CXCR6 ranged between 5-25%." (PMID 35464424, 2022). "Despite high proportions of T cells and non-lymphocyte populations identified as positive for CCR6 and CCL20 via scRNA-seq respectively, CCR6+ T cells were not enriched in glioblastoma and we were unable to detect CCL20 in supernatants via ELISA." (PMID 35464424, 2022).
hyper-IgE syndrome (2 papers, 2016 to 2021). A condition that is characterized by elevated serum IgE, dermatitis, and respiratory infections. "Furthermore, analyses of blood from patients with Hyper-IgE Syndrome (HIES), caused by dominant negative Stat3 mutations, showed normal Treg percentages but significant reduction of Treg expressed CCR6." (PMID 27974866, 2016). "Additionally, Tregs from patients with Hyper-IgE Syndrome (HIES), a primary immunodeficiency caused by dominant negative STAT3 mutations, showed significantly reduced surface expression of CCR6." (PMID 33315130, 2021).
Insulin resistance (2 papers, 2016 to 2024). Increased resistance towards insulin, that is, diminished effectiveness of insulin in reducing blood glucose levels. "Our data suggest that PT has the potential to regulate insulin resistance and metabolic syndrome by lowering the mRNA expression of PDPK-1, CCR4, CCR6, and CCL4L2 in PBMCs." (PMID 27869712, 2016).
kidney damage (2 papers, 2018). "Combination of CCL20 with CCR6 (the CCL20 receptor) cause the recruitment of leukocyte subsets, which finally promote immune-mediated kidney damage." (PMID 30029622, 2018).
laryngeal squamous cell carcinoma (2 papers, 2019 to 2025). A squamous cell carcinoma that arises from the larynx. "A study on laryngeal squamous cell carcinoma has shown that chemokine receptors CCR6/CCR7 and their ligands CCL19/CCL20 synergically drive cervical lymph node metastasis of laryngeal squamous cell carcinoma through differential expression and Treg recruitment." (PMID 41445742, 2025). "The chemokine receptors CCR6 and CCR7 have been reported to be involved in the presence of Foxp3+ Treg cell in favor of progression of laryngeal squamous cell carcinoma." (PMID 30216450, 2019).
lichen planus (2 papers, 2020). A chronic, recurrent, pruritic inflammatory disorder of unknown etiology that affects the skin and mucus membranes. "In parallel, the increased expression of CCL20 and CCR6 has been demonstrated in lichen planus which also manifests Koebnerization." (PMID 31936670, 2020).
MALT lymphoma (2 papers, 2021 to 2022). An indolent, extranodal type of non-Hodgkin lymphoma composed of small B-lymphocytes (centrocyte-like cells). "Interestingly, distinct mutation profiles, corresponding to clusters of nonsense and frameshift mutations in the C-termini of GPCRs, GPR34, CCR6, and CCR4, have been reported in mucosa-associated lymphoid tissue (MALT) lymphoma and adult T cell leukemia/lymphoma (ATLL) as gain-of-function mutations." (PMID 34852802, 2021). "Four genes recently described to be mutated in the non-pSS MALT lymphoma of the salivary gland, TBL1XR1, CCR6, TNFAIP3 and NOTCH2, were also mutated in a subset of our pSS-MALT lymphomas." (PMID 35205758, 2022).
metastatic carcinoma (2 papers, 2012 to 2023). A carcinoma which has spread from the original site of growth to another anatomic site. "This hypothesis is not supported by our research results because we showed that the expression level of CCR6 mRNA was higher in NSCLC patients with diagnosed lymph nodes metastasis (N1 + N2) compared to non-metastatic cancer patients (N0)." (PMID 37316552, 2023).
monocyte leukemia (2 papers, 2016 to 2021). "CCR6DNP/TG beads were incubated with nuclear extract from THP-1 cells, a human monocyte leukemia line expressing of CCR6." (PMID 27626929, 2016).
osteoporosis (2 papers, 2016 to 2023). A condition of reduced bone mass, with decreased cortical thickness and a decrease in the number and size of the trabeculae of cancellous bone (but normal chemical composition), resulting in increased fracture incidence. "Our findings suggest that monocytes expressing both RANK and CCR6 play a pivotal role in the joint destruction of RA and osteoporosis." (PMID 27822475, 2016). "RANK and CCR6 expressed on monocytes may be novel targets for the regulation of bone resorption in RA and osteoporosis." (PMID 27822475, 2016).
parasitemia (2 papers, 2012 to 2022). "Our data argue for CCR6 playing a role in Treg cell rather than Th17 cell recruitment during parasitic infections that depend on cell-mediated immune response as the predominant protective immune mechanism." (PMID 23028548, 2012).
pneumococcal meningitis (2 papers, 2014 to 2017). An acute purulent infection of the meninges and subarachnoid space caused by Streptococcus pneumoniae, most prevalent in children and adults over the age of 60. "CCR6-deficient mice with pneumococcal meningitis and WT mice with pneumococcal meningitis treated with anti-CCL20 antibodies both had reduced CSF white blood cell counts." (PMID 24699535, 2014). "The neutrophil response in pneumococcal meningitis that is guided to the subarachnoid space through the chemokine/receptor pair CCL20/CCR6 is important for limiting bacterial outgrowth." (PMID 24699535, 2014). "This missing difference in brain IL-22 levels argues against a critical role of this TH17-cytokine as a downstream mediator of CCL20/CCR6-induced leukocyte recruitment to the CSF in pneumococcal meningitis." (PMID 24699535, 2014). "Thus, IL-17 does not seem to mediate the pro-inflammatory effect of the CCL20/CCR6 axis in pneumococcal meningitis." (PMID 24699535, 2014). "Here we studied the role of CCL20 and its receptor CCR6 in pneumococcal meningitis." (PMID 24699535, 2014). "Thus, IL-17A/F seems unlikely to be involved in the chemoattractant activity of the CCL20/CCR6 axis during pneumococcal meningitis." (PMID 24699535, 2014). "Combined with the observation that blockage of CCL20 and deficiency of CCR6 reduced CSF pleocytosis after intracisternal pneumococcal challenge, our data indicate a crucial role of CCL20 in the recruitment of granulocytes to the subarachnoid space during pneumococcal meningitis." (PMID 24699535, 2014).
primary biliary cholangitis (2 papers, 2024). Primary biliary cholangitis (PBC) is a chronic and slowly progressive cholestatic liver disease of autoimmune etiology characterized by injury of the intrahepatic bile ducts that may eventually lead to liver failure. "The biliary epithelial cells release CC chemokine receptor 6 (CCR6) ligand 20 (CCL20), leading to recruitment of CCR6+ T cells and subsequent infiltration into the biliary epithelium in primary biliary cholangitis patients." (PMID 38405661, 2024).
pulmonary arterial hypertension (2 papers, 2020 to 2025). Pulmonary arterial hypertension (PAH) is a group of diseases characterized by mean pulmonary artery pressure >20 mmHg and elevated pulmonary arterial resistance leading to right heart failure. "Of these chemokines and chemokine receptors, Ccl2, Ccl7, Ccl20, Ccl21, Cxcl13, Cxcl4, Ccr6 and Ccr7 have already been demonstrated to be associated with pulmonary hypertension." (PMID 32176619, 2020). "In contrast, endothelial cells largely express several other chemokine receptors including CCR4, CCR5, CCR6, CXCR2, CXCR4, and CXCR5, and CXCR4, which plays a key role in pulmonary arterial hypertension (PAH) through an autocrine signaling mechanism." (PMID 40859641, 2025).
respiratory infection (2 papers, 2021 to 2024). "Here, we observed that respiratory infections in nursing infants also induced higher CCL20 concentrations in breast milk, leading to an increase in all CCR6+ T- and B-cell subpopulations." (PMID 39867906, 2024).
retinal degeneration (2 papers, 2019 to 2025). Degeneration of the retina. "CCR6−/− mice showed reduced retinal degeneration, microgliosis, and inflammation." (PMID 31151410, 2019).
squamous carcinoma (2 papers, 2013 to 2024). "Fibroblast lines derived from the lungs of patients suffering from squamous carcinoma expressed only background levels of CCR6 mRNA." (PMID 38334630, 2024). "A number of chemokine/chemokine receptor antagonists are being developed for tumour immunotherapy and it remains to be seen whether blocking of CCR6/CCL20 would impact on immunosuppression in squamous cell cancers." (PMID 23469070, 2013).
type 2 diabetes (2 papers, 2016 to 2025). "In addition, CCR4 and CCR6 are more expressed in type 2 diabetes patients than in non-diabetic persons." (PMID 27869712, 2016).
typhoid fever (2 papers, 2017 to 2022). A bacterial infectious disorder contracted by consumption of food or drink contaminated with Salmonella typhi. "Interestingly, MAIT cells from low-dose TD volunteers had higher levels of CD38 coexpressing CCR9, CCR6, and Ki67 during the development of typhoid fever than high-dose TD volunteers." (PMID 28428786, 2017). "Interestingly, we found that TD volunteers exposed to low doses of wild-type S. Typhi (103 CFU) had higher levels of CD8+ MAIT cells coexpressing CD38 and either CCR9, CCR6, or Ki67 during the development of typhoid fever than TD volunteers receiving a high dose of S. Typhi (104 CFU)." (PMID 28428786, 2017). "Previously, we found that during typhoid fever, activated MAIT cells expressing CD57, CCR6, or CCR9 increased in all TF participants." (PMID 35772315, 2022). "Here, we report that activated (CD38+) MAIT cells coexpressing CCR6 and CCR9 markers were significantly higher during typhoid fever in TD volunteers receiving the low-dose inoculum than in TD volunteers receiving the high-dose inoculum." (PMID 28428786, 2017). "Moreover, the magnitude of MAIT cells coexpressing CCR6 and CCR9 markers were significantly higher, during typhoid fever, in TD volunteers receiving the low-dose inoculum than in TD volunteers receiving the high-dose inoculum." (PMID 28428786, 2017).
VKH syndrome (2 papers, 2013 to 2015). "In conclusion, this study indicates that the A allele of the FGFR10P tagSNP rs2301436, but not rs3093024, rs6902119, rs3093023 and rs968334 in the CCR6 gene, is associated with susceptibility to VKH syndrome in Chinese Han." (PMID 23935994, 2013).
acute GVHD (1 paper, 2024). "The experiment showed that recipient mice receiving transplants from CCR6-deficient donors experienced delayed onset and relatively mild symptoms of acute GVHD, suggesting that CCR6 may be a potential chemokine receptor target for the prevention and treatment of acute GVHD." (PMID 39840040, 2024).
acute kidney injury (1 paper, 2025). Sudden and sustained deterioration of the kidney function characterized by decreased glomerular filtration rate, increased serum creatinine or oliguria. "CC motif chemokine ligand 20 (CCL20), a chemokine involved in immune cell migration through its receptor CCR6, has been implicated in kidney inflammation in crescentic glomerulonephritis and acute kidney injury." (PMID 41226600, 2025).
AIDS (1 paper, 2021). A syndrome resulting from the acquired deficiency of cellular immunity caused by the human immunodeficiency virus (HIV). "In animal models, the expression of both MIP-3α and CCR6 are increased in acutely infected macaques and decreased in macaques with AIDS." (PMID 35055955, 2021).
airway hyperresponsiveness (1 paper, 2009). "In mouse models of immune response and diseases, CCR6 and/or MIP-3α/CCL20 were required in allergic pulmonary inflammation and contributed to ozone-induced airway hyperresponsiveness and the pathogenesis of cigarette smoke-induced pulmonary inflammation." (PMID 23283206, 2009).
alcoholic cirrhosis (1 paper, 2021). "Neither did we observe any elevated expression of CCR6 or CXCR6 on circulating MAIT cells in patients with alcoholic cirrhosis or mixed cirrhosis." (PMID 34321090, 2021).
allergic conjunctivitis (1 paper, 2018). "Allergic conjunctivitis is an inflammatory disorder of the ocular surface that is characterized by Ig E and T helper lymphocyte-2 (TH2) driven allergic responses, which are marked by eosinophilic infiltration of the conjunctiva and involve the chemokine receptor CCR6." (PMID 30453514, 2018).
alopecia areata (1 paper, 2022). Loss of scalp and body hair involving microscopically inflammatory patchy areas. "People with alopecia areata (AA) have increased proportions of circulating CCR6+ “Th17” and CXCR3+CCR6+ “Th1/17” CD4 T cells, which are elevated significantly more often in individuals with <50% hair loss, indicating that the early stages of the disease may be more immunologically active." (PMID 36200950, 2022).
aneurysm (1 paper, 2024). Bulging or ballooning in an area of an artery secondary to arterial wall weakening. "CCR6 (CC chemokine receptor 6), which is highly expressed in the aneurysmal wall, contributes to aneurysm development by promoting the migration of T cells and natural IL-17–producing γδ T cells." (PMID 39737187, 2024).
Arthralgia (1 paper, 2022). "Psoriasis patients without arthralgia had lower numbers of CCR6-CCR4+CXCR3+ memory Th cells and higher numbers of CCR6+CCR4-CXCR3-memory Th cells compared to HC." (PMID 35045868, 2022).
asthenozoospermia (1 paper, 2017). "This led us to speculate that spermatozoa obtained from asthenozoospermia patients with reduced levels of either CCR6 or CatSper should also exhibit defects in hyperactivation and acrosome reaction." (PMID 29207656, 2017).
autoimmune thyroid disease (1 paper, 2015). Inflammatory disease of the thyroid gland due to autoimmune responses leading to lymphocytic infiltration of the gland. "This study was conducted to identify the association of CCR6 and RNASET2 tag SNP with autoimmune thyroid diseases (AITDs) in the Chinese Han population." (PMID 25928629, 2015).
brain injury (1 paper, 2024). Acute and chronic (see also brain INJURIES, CHRONIC) injuries to the brain, including the cerebral hemispheres, CEREBELLUM, and brain STEM. "However, it is still necessary to test whether and how blocking CCR6 and CCR8 affects the activities of their endogenous ligands, which are known to be upregulated, as is well documented for CCL1 and CCL20 after nerve and brain injury, respectively." (PMID 38612597, 2024).
bronchial carcinoma (1 paper, 2024). "In contrast, in tumour-free lung tissue samples from a bronchial carcinoma patient, no CCR6 expression could be detected." (PMID 38334630, 2024).
cerebral infarction (1 paper, 2022). An ischemic condition of the brain, producing a persistent focal neurological deficit in the area of distribution of the cerebral arteries. "We have shown that deletion of Htr7 and Ccr6 in Tregs markedly reduced their ability to infiltrate and proliferate in the brain after cerebral infarction." (PMID 35911740, 2022).
cervical intraepithelial neoplasia (1 paper, 2021). "In this context, we evaluated the distribution of CD45RA+ and CD45RO+ cells as well as CCR6+ and CCL20+ cells in intraepithelial (IE) and marginal stroma (MS) areas from cervical intraepithelial neoplasia (CIN) I–III, and CC as ‘immunoscore’ for HPV-induced CC outcome." (PMID 33888832, 2021).
Cholestatic liver disease (1 paper, 2023). "Consistent with the findings in a mouse model, patients with cholestatic liver disease showed elevated CCR6 expression, which linked CCL20 to biliary epithelial cells (BECs); however, these were considered as Th17-dominated." (PMID 37475963, 2023).
chronic GVHD (1 paper, 2012). "Distinctively, CD161-expressing T cells display high levels of the chemokine receptor CCR6, for which we recently showed that a single nucleotide polymorphism in this gene correlates with occurrence of chronic GVHD." (PMID 23226545, 2012).
chronic lymphocytic leukemia (1 paper, 2020). "In addition, a genome-wide DNA methylation analysis of chronic lymphocytic leukemia patients in comparison to healthy donors identified the differently methylated CCR6 gene, among other immune regulatory genes." (PMID 32961999, 2020).
Cognitive impairment (1 paper, 2022). Abnormal cognition is characterized by deficits in thinking, reasoning, or remembering. "We suggest that the inhibition of overexpression of Lin28a induced by chronic cerebral hypoperfusion can alleviate VaD-related cognitive impairment by reducing the activation of astrocytes and CCR6 and by ameliorating BBB disruption." (PMID 35453602, 2022).
coronary artery atherosclerosis (1 paper, 2021). "Interestingly, GM of CCR6 on B-1 cells was significantly lower in patients with high GS, suggesting that CCR6 expression on human B-1 cells may protect from development of severe coronary artery atherosclerosis." (PMID 33679793, 2021).